ANGPTL6 (angiopoietin like 6)
Diseases named in the same sentence as ANGPTL6 in open-access papers (continued):
Sharing a sentence is not in itself a finding about the gene and the disease.
renal carcinoma (1 paper, 2023). A carcinoma arising from the epithelium of the renal parenchyma or the renal pelvis. "However, the expression of ANGPTL6 in normal renal tissue was higher than that in renal carcinoma tissue." (PMID 37260987, 2023). "However, similar to ANGPTL6, the expression of PKHD1L1 in normal kidney tissues was higher than that in renal cancer tissues, and the high expression of PKHD1L1 also predicted a poor prognosis." (PMID 37260987, 2023).
Tinnitus (1 paper, 2023). Tinnitus is an auditory perception that can be described as the experience of sound, in the ear or in the head, in the absence of external acoustic stimulation. "Meanwhile, down-regulated genes between the tinnitus and the control group were Car3, Egr2, Bcl6b, C1qtnf12, Cartpt, LOC108348062, Nr4a3, Gprc5a, LOC103690128, and Angptl6." (PMID 37190538, 2023).
tumor (8 papers, 2012 to 2024). "The TT genotype-associated decreased risk of HCC appears to be related to lowered CYP2D6 activity and altered protein expression in the tumor microenvironment, and ANGPTL6 is a promising new diagnostic and prognostic biomarker for HCC." (PMID 34412629, 2021). "In addition, high expression of ANGPTL6 in tumor tissues was associated with a poor prognosis." (PMID 37260987, 2023). "The study found that high AFP levels correlate with the expression of ANGPTL6, a protein that promotes angiogenesis and tumor progression by activating the ERK1/2 and AKT signaling pathways." (PMID 39685591, 2024). "The correlation between ANGPTL6 and tumor has been reported." (PMID 37260987, 2023). "Moreover, the significant downregulation of ANGPT2, ANGPT2, ANGPTL1, ANGPTL4, and ANGPTL6 was found in tumor-adjacent tissues." (PMID 34685578, 2021). "Vessel-enriched angiopoietin-like 6 might be secreted by (primary or metastatic) tumour cells; alternatively, it might be induced in normal liver cells by tumour-derived factors." (PMID 23070965, 2012). "It was suggested that ANGPTL6 might have a complicated effect on tumor diagnosis and progression." (PMID 37260987, 2023). "We found that ANGPTL1, ANGPTL3, ANGPTL4, ANGPTL6, and ANGPTL7 were differentially expressed between tumor and normal tissues." (PMID 35692877, 2022). "Meanwhile, paraffin specimen analysis further confirmed these results and demonstrated almost no expression of ANGPTL6 in tumor cores." (PMID 34412629, 2021).
cancer (4 papers, 2012 to 2022). A tumor composed of atypical neoplastic, often pleomorphic cells that invade other tissues. "Finally, with the exception of ANGPTL3, the remaining genes showed significant correlations with cancer-associated fibroblasts, endothelial cells, and microenvironment score, whereas only ANGPTL6 was significantly correlated with immune score." (PMID 34685578, 2021). "Although the overall staining for angiopoietin-like 6 in hepatocytes was similar, this ligand significantly accumulated in hepatic blood vessels of cancer patients in comparison to those of healthy individuals." (PMID 23070965, 2012). "Indeed, besides angiopoietin-like 6, a number of extracellular proteins share similarity with the metastasis-specific peptides, among which a proteoglycan (perlecan) and a component of the basal lamina (laminin α2), both involved in angiogenesis and cancer progression." (PMID 23070965, 2012).
metabolic disease (3 papers, 2017 to 2021). A congenital disorder (due to inherited enzyme abnormality) or acquired (due to failure of a metabolically important organ) disorder resulting from an abnormal metabolic process. "As part of a mechanistic study for ANGPTL6 regulation, we have previously found that exercise training lowers serum ANGPTL6 levels in sedentary subjects not having a medical history of metabolic diseases, and its alteration is linked to leptin." (PMID 33668309, 2021).
ANGPTL6 also shares sentences with these, for which no sentence is quoted: Hepatic steatosis (3 papers); diabetes (2); hepatocellular carcinoma (2); Hyperglycemia (2); age-related macular degeneration (1); aneurysm (1); atherosclerosis (1); breast carcinoma (1); central obesity (1); gestational diabetes mellitus (1); Impaired glucose tolerance (1); inflammatory bowel disease (1); ischemia (1); leprosy (1); liver cancer (1); myocardial infarction (1); Nephropathy (1); Parkinson's (1); preeclampsia (1); steatosis (1); Stroke (1); triple-negative breast carcinoma (1).